STAT3 (signal transducer and activator of transcription 3)
Diseases named in the same sentence as STAT3 in open-access papers (continued):
Sharing a sentence is not in itself a finding about the gene and the disease.
cancer (continued). "Epigenetic changes play an important role in the abnormal activation of the IL-6/IL-6R/JAK/STAT3 pathway in cancer, and changes in transcription factor expression and/or activation may be involved in cancer progression." (PMID 33363013, 2020). "Inhibition of STAT3 in wide range of cancer cell lines with small molecular inhibitors, dominant‐negative mutants, and small interfering RNA (siRNA) results in a decline in cell proliferation, indicating that STAT3 is a potential target for anticancer therapies." (PMID 32495998, 2020). "In several cancers, apoptosis is downregulated by the cytosolic transcription factor STAT3." (PMID 33081075, 2020). "Activated STAT3 and NF-κB crosstalk to promote cancer progression." (PMID 32204484, 2020). "qPCR analysis showed that remarkably higher level of STAT3 was detected in clinical cancer samples." (PMID 33390934, 2020). "Next, we disrupted the STAT3 pathway to verify whether STAT3 is the most important effector of FOXD2-AS1 in cancer stemness and chemoresistance regulation." (PMID 31959918, 2020). "Along with several signaling pathways that regulate various MMPs, there are also various transcription factors such as nuclear factor kB (NF-kB) and signal transducer and activator of transcription-3 (STAT-3), that transcribe various MMPs with a role in the metastasis in cancer." (PMID 32466129, 2020). "ETO treatment of cancer cells activates the IL-6/JAK1/STAT3 pathway that may mediates communication between tumor cells and the microenvironment." (PMID 32059469, 2020). "For instance, STAT3 orchestrates the fine-tuning activity of macrophages in cancer." (PMID 33584695, 2020). "Therefore, STAT3 is considered to be an important target for the development of cancer therapeutic agents." (PMID 33053804, 2020). "Cancer-induced factors manipulate also DCs differentiation by a STAT3-dependent signaling pathway." (PMID 33584695, 2020). "Indeed, STAT3 is also important for initiating the epithelial-mesenchymal transition (EMT) program, which is associated with cancer therapy resistance." (PMID 32872659, 2020). "Emerging studies suggest that STAT3 activation induces the expression of PD-L1 in various cancers." (PMID 32477934, 2020). "With STAT3 now linked to HR impairment and BRCAness in EBV-transformed cells and also known to be constitutively active in a variety of cancers, we asked if a STAT3-gene signature could predict susceptibility of cancers to synthetic lethal approaches." (PMID 33002095, 2020). "Therefore, this is an intriguing future prospect for targeting STAT3 as a mediator of cancer progression." (PMID 32731620, 2020). "Metformin reduces STAT3 activity in cancer cells and CSCs including glioblastoma and MM." (PMID 32751207, 2020). "Unpredicted functions of various components and miRNAs that have been identified as new positive or negative regulators of STAT3 may need further investigations, for us to be able to selectively target JAK/STAT3 signaling for cancer therapy." (PMID 31952344, 2020). "Additionally, RhoC is known to influence STAT3 in cancer, a relationship that can be blocked by drugs that affect lipid modification and therefore membrane localisation and activation of Rho-family proteins." (PMID 32915198, 2020). "STAT3 acetylation is found to regulate the proliferation of cancer cell." (PMID 33382817, 2020). "Therefore, the inhibition of the homodimerization of STAT3 has been considered as a rational strategy in the management of cancer." (PMID 33053804, 2020). "Constitutively activated STAT3 has been identified in certain types of cancer, including ESCC." (PMID 32194797, 2020). "Reported cooperation between CD44 and STAT3 in different cancer models." (PMID 33335857, 2020). "It is therefore, believed that novel bioactive molecules possessing potent anticancer and anti-STAT3 activity could effectively set the cancer cells on the road to ruin and could be potentially developed into novel anti-cancer drugs." (PMID 32328177, 2020).
cancer (continued). "Moreover, STAT3 negatively regulates gene expression in MEFs and cancer lines to control type I IFN-mediated antiviral response." (PMID 33256738, 2020). "Additionally, IL‐6 and IL‐11 activate STAT3 signalling, which works with NF‐κB to promote cancer development." (PMID 32347623, 2020). "Inhibition of these kinases may therefore be alternative strategies to inhibit STAT3 in cancers and other pathological conditions." (PMID 32231398, 2020). "STAT3 acts as a key oncogenic factor regulating survival, proliferation, migration, and invasion of cancer cells; accordingly, AsiC-treated cells showed a strong reduction in cell viability, the activation of programmed cell death, and a less migratory ability compared to negative controls." (PMID 32957732, 2020). "The transcriptional activator STAT3 regulates several oncogenes in a range of human cancers." (PMID 32503225, 2020). "Overall, these data laid the foundation for the study that betulinic acid and cucurbitacin I might regulate STAT3 in cancer." (PMID 32486001, 2020). "Moreover, CD44-mediated signaling interacts with other well-known pro-tumorigenic pathways and oncogenes during cancer development, such as signal transducer and activator of transcription 3 (STAT3)." (PMID 33335857, 2020). "STAT3 is becoming a promising target in the radiosensitization of cancer." (PMID 32733808, 2020). "Nanog mRNA expression, which often occurs in melanocytes early in development, as well as the expression of Stat3 and VEGF, which are often associated with cancer survivability, were increased in late melanosphere passages compared to similar passages of WT cells." (PMID 32224883, 2020). "More studies are warranted in the future to verify whether targeting STAT3 is efficient in inhibiting irradiation-induced malignant behaviors of cancers." (PMID 32733808, 2020). "In addition, CSCs or stemness-high cancer cells are extremely sensitive to the direct inhibition of STAT3 but insensitive to the inhibition of upstream factors like Janus kinases." (PMID 33343368, 2020). "Furthermore, accumulating evidence has indicated that IL-6 is a potent inducer of epithelial to mesenchymal transition (EMT) in various carcinomas via the signal transducer and activator of transcription 3 (Stat3)/Snail signaling pathway." (PMID 32570756, 2020). "STAT3 contributes to chemo(radio)resistance in various carcinoma types." (PMID 32872659, 2020). "Previous studies have shown that STAT3 is a therapeutic target in a broad spectrum of cancers." (PMID 31277685, 2019). "STAT3’s activity in cancer is generally viewed as oncogenic." (PMID 30782607, 2019). "Consequently, it potentiates the inhibitory effect of IFN-α, a potent antiproliferative factor, on cancer cell viability by activating JAK2/STAT3 signaling pathway through inhibition of 26S proteasome-mediated IFNAR1 degradation." (PMID 31100782, 2019). "STAT3, STAT5A and STAT5B have been implicated in several physiological and disease processes such as cell division, migration, survival, cellular responses to pathogens, breast development, inflammation and cancer." (PMID 31443474, 2019). "Moreover, chip-PCR analysis showed that STAT3 bind directly the FOSL1 gene promoter in cancer cell lines stimulated with IL6." (PMID 31438567, 2019). "Attenuation of metastasis and induction of apoptosis by RCFE might be attributed to its activity to down regulate phosphorylation of STAT3, a master regulator for these two pathways in cancer cells." (PMID 31601896, 2019). "The pivotal role of STAT3 in the regulation of epithelial-to-mesenchymal transition (EMT) in GC, a fundamental process that enables cancer cells to obtain mesenchymal properties, including loss of contact inhibition and increased motility, allowing them to disseminate, has been previously revealed." (PMID 31234597, 2019).
cancer (continued). "Gemcitabine could promote the binding of phosphorylated STAT3 to the Bmi1 promoter, which further enhances the stemness and migration of cancer cells." (PMID 31244991, 2019). "While persistent activation of both STAT3 and STAT5 has been implicated in the transformation process, the greater impact of dysregulated STAT3/5 appears to be their influence on the induction of aggressive cancer cell properties and immunosuppression." (PMID 31684144, 2019). "It is now well-established that STAT3 signaling is a major intrinsic pathway driving apoptosis, inflammation, cellular transformation, survival, proliferation, invasion, angiogenesis and metastasis in cancer." (PMID 31480382, 2019). "As opposed to mutation rates, STAT3/5 activation is very frequent in human cancers, perhaps reflecting increased cytokine signaling or mutations in cytokine receptors or negative regulators." (PMID 31557897, 2019). "In the following experiments, we made efforts in examining the regulatory effects that BMX-ARHGAP had on the GC stem cell markers and their properties, and analyzing the potential regulatory network of BMX-ARHGAP/SH2/JAK/STAT3 to provide an anti-cancer target for cancer treatment." (PMID 31130822, 2019). "In this study, we show that FOXL2 could be regulated by STAT3 in cancer cells and that STAT3 binds to FOXL2 at the 5′- GCCTGATGTTTGTCTTCCCAGTCTGTGGCAA-3′ site using EMSA and ChIP." (PMID 31221094, 2019). "NF-κB and STAT3 signalling pathways collaboratively link inflammation to cancer." (PMID 30886235, 2019). "Given that targeting STAT3 by the STAT3 inhibitors such as C188-9 has been evaluated in early phase clinical trials for advanced-stage cancers (NCT03195699), it should be taken into caution for the rational design of combinatorial approaches using chemotherapy to boost oncolytic NDV-induced ICD." (PMID 31192135, 2019). "Many STAT3-targeted therapies have been successfully developed and shown efficacy in preclinical models of TNBC in vitro and in vivo; several STAT3 inhibitors even enter clinical trials and are currently under investigation in various human cancers, including TNBC." (PMID 31088482, 2019). "Given that STAT3 has recently been shown to play a critical role in mitochondrial and metabolic activity in the development of cancers, it would be intriguing to determine whether STAT3-dependent metabolic changes contribute to sexual dimorphism in SHH MB." (PMID 31683879, 2019). "Drugs acting on STAT3/5 and their regulators may restore the control of cell proliferation in cancer cells." (PMID 31557897, 2019). "Moreover, STAT3 in cancer cells affects stromal cells function, establishing crosstalk between cancer cells and its microenvironment." (PMID 31480382, 2019). "Compound 19 reduced cancer stem cell populations and deactivated STAT3 and NF-κB." (PMID 31360301, 2019). "In cancer cells, inhibition of HNF4α leads to an inflammatory-response-mediated regulatory feedback loop initiating and maintaining hepatocellular carcinogenesis via STAT3-mediated induction of miR-24 and miR-629 expression." (PMID 31557902, 2019). "Furthermore, in respect to the role of STAT3 in inducing the expression of anti-apoptotic factors such as Bcl-xL and survivin, down-regulation of STAT3 is related to the decreased viability and proliferation of cancer cells." (PMID 31569687, 2019). "However, most of them have also been found to inhibit other signaling pathways that are triggered by ligand-cell surface receptor binding in cancer cells, indicating a low level of specificity in targeting the STAT3 signaling pathway." (PMID 31088482, 2019).
cancer (continued). "Therefore, our discovery of the JAK2/STAT3/CCND2 axis in CSCs will have broad applications in multiple types of cancers." (PMID 31511084, 2019). "Further investigations on biomarkers of STAT3 activation may be helpful in identifying cancer patients for STAT3-targeted therapies and thus improve clinical outcomes." (PMID 31731457, 2019). "Dysregulation of JAK2/STAT3 signaling pathway has been described in many cancers including NSCLC." (PMID 31754348, 2019). "Additionally, the study demonstrated that STAT3 was a target of GSK3β using cancer phospho-antibody array and that enhanced GSK3β expression promoted ESCC progression through STAT3 in vitro and in vivo." (PMID 31888532, 2019). "Given the emerging role of HSP110 in cancer and its role on STAT3 in particular, we selected two foldamers upon screening of a chemical library based on their ability to inhibit and block recombinant HSP110-mediated antiaggregation activity and to disrupt HSP110–STAT3 interaction." (PMID 31861612, 2019). "2-Ethoxystypandrone may be considered as a novel STAT3 signaling inhibitor lead compound for developing anti-cancer agents targeting HCC CSCs." (PMID 30709346, 2019). "Aberrant STAT3 activity is observed in around 50% of all cancers including those of the CNS." (PMID 31683879, 2019). "In addition, activation of the STAT3-MMP axis has been reported to promote cancer cell invasiveness and metastasis." (PMID 31221177, 2019). "Therefore, inhibition of STAT3 signaling effectively eliminates the formation of the metastatic niche, and it suppresses cancer cell persistence after chemotherapy." (PMID 31861720, 2019). "STAT3 inhibitors and IL-15C have also shown promise in therapeutic approaches to treat cancers." (PMID 31552035, 2019). "Hence, targeting STAT3 has become a major endeavor in cancer therapy and efforts to reduce STAT3 signaling using nanoparticles have been attempted." (PMID 30959799, 2019). "Anti-cancer effects of hispidulin are mediated by multiple signaling mechanisms, including inhibition of Akt, signal transducer and activator of transcription 3 (STAT3), and aurora kinase, and activation of AMP-activated protein kinase (AMPK)." (PMID 31817696, 2019). "Evidence suggests a role of STAT-3 protein phosphorylation/activation in cancer cell survival." (PMID 30654529, 2019). "Ursolic acid is another candidate as it inhibited cancer metastasis by targeting STAT3 or Src." (PMID 31067694, 2019). "Moreover, it has been demonstrated that the STAT3 pathway is involved in cancer stem cell (CSC) self-renewal and cancer chemoresistance." (PMID 31126035, 2019). "The STAT3 signaling pathway regulates cancer cell proliferation and apoptosis." (PMID 32010177, 2019). "Thus, the present study investigated the role of STAT3 and G9a in cancer stemness and HER3 expression." (PMID 31619200, 2019). "STAT3 signalling is considered immunosuppressive and may protect cancer cells from recognition and lysis by cytotoxic T lymphocytes, achieved by triggering production of cytokines, including IL-6, IL-10, VEGF and TGF- β175." (PMID 31308358, 2019). "As an essential mediator of inflammatory responses and activator of STAT3, IL‐6 could impair apoptosis in cancer cells." (PMID 31246342, 2019). "In conclusion, these findings comprehensively demonstrate that BT may act as an effective inhibitor of STAT3 signaling and it can be a promising drug to test in other STAT3 overexpressing preclinical cancer models." (PMID 31575007, 2019). "Therefore, targeting STAT3 is an attractive approach given that it assaults cancer on multiple fronts." (PMID 31456939, 2019). "Thus, flubendazole is a potential drug candidate for CRC and other cancers, which acts by inhibiting STAT3 signaling and activating autophagy." (PMID 31287013, 2019). "Targeting STAT3 is a promising therapeutic strategy in many types of cancer patients." (PMID 31684051, 2019).
cancer (continued). "They tested their antiproliferative activity in human cancer cells lines of prostate (DU-145) and colon (HT-29) obtaining positive results, which suggests that STAT3 could be one of the many targets of this class of compounds and a new line to exploit." (PMID 31388334, 2019). "STAT-3 is a pleiotropic transcription factor, recognized as an oncogene in various cancers." (PMID 31555270, 2019). "Furthermore, we unveiled the novel miR-365-3p/EHF/KRT16/β5-integrin/c-Met pathway capable of regulating OSCC cell migration, invasion, metastasis, and cancer stemness by activation of the Src/STAT3 signaling." (PMID 30782177, 2019). "Identifying non-STAT3 downstream effectors/signaling pathways specifically mediated by LIF can be beneficial for evaluating therapeutic efficiency of LIF blockade in KRAS mutant cancers." (PMID 31296870, 2019). "It has been shown that Nanog and Stat-3 are functionally coupled in many cancer cells." (PMID 31293964, 2019). "The NFκB–IL-6—STAT3 signalling axis is important to cancer biology." (PMID 31226168, 2019). "The downregulation of both AP-1 and STAT3 results in retardation of the growth of cancer cells." (PMID 30890933, 2019). "It is thus suggested that targeted disruption of STAT-3 could be one potential approach to treat human cancers overexpressing STAT-3." (PMID 30654529, 2019). "Thus, the different actors of the mammary adipose microenvironment and the cancer cells themselves can activate the STAT3 pathway in an autocrine or paracrine manner." (PMID 31756890, 2019). "ERBB inhibition blocked phosphorylation of STAT3 and arrested cancer cells." (PMID 30645971, 2019). "Hence, inhibiting the STAT3 signaling axis has gradually emerged as an important strategy for the treatment of cancer." (PMID 31287013, 2019). "To date, STAT3 is widely recognized as an oncogenic factor in diverse human cancers." (PMID 31731457, 2019). "We hypothesize that the endogenous tonic interferon-STAT-MHC class I axis in DFTD is disrupted due to high STAT3 action promoting cancer cell proliferation, survival, and invasion." (PMID 30645971, 2019). "The IL-6R/STAT3/miR-34a loop mediates cancer invasion and metastasis." (PMID 30885232, 2019). "In this review, we mainly focused on the chaperones HSP90, HSP70, HSP110, and HSP27 and their regulation of protein misfolding and signaling in TYK2-STAT3/5 core cancer pathways, as well as the possibility of targeting such HSPs to specifically restrain STAT3/5 oncogenic functions." (PMID 31861612, 2019). "Therefore, inhibiting NF-κB and STAT3 signaling has potential therapeutic applications for cancer stem cells." (PMID 31360301, 2019). "Therapeutic resistance that is mediated by STAT3 in oncogene-driven cancers has also been observed." (PMID 31842362, 2019). "STAT3 activates distinct transcriptional programmes within cancer cells." (PMID 31399589, 2019). "Moreover, we observed that the effects induced in cancer cells are mediated by the exosome-depending activation of STAT-3 signal transduction pathway." (PMID 31697737, 2019). "A sexually dimorphic requirement for STAT3 in cancer was observed previously." (PMID 31683879, 2019). "Although therapies are not currently available, strategies to target the NFκB–IL-6 –STAT3 signalling axis may benefit the treatment of HPV+ cancers." (PMID 31226168, 2019). "Collectively, IL-6, through the synergistic action of NF-κB and STAT3 TFs, together with the functions of miR-21, miR-181b-1, and let-7, establishes a feedback mechanism to sustain inflammatory signals to directly link chronic inflammation and cancer." (PMID 31557902, 2019). "STAT3 induces expression of MMPs and promotes invasion and metastasis in cancer cells." (PMID 31601896, 2019). "STAT3 has been proposed as a particularly attractive target for potential cancer therapy." (PMID 31885879, 2019). "Hence, it is possible that STAT3 activation is a common signaling intermediate that leads to the overexpression of MMP9 in malignant tumors." (PMID 31456939, 2019).